EGFR (epidermal growth factor receptor)
Diseases named in the same sentence as EGFR in open-access papers (continued):
Sharing a sentence is not in itself a finding about the gene and the disease.
adenocarcinoma (continued). "In patients with adenocarcinoma, EGFR, ALK, and ROS1 mutations as well as PD-L1 expression were mostly tested using single biomarker assays, such as Sanger sequencing, reverse transcriptase-polymerase chain reaction, immunohistochemistry, and fluorescent in situ hybridization." (PMID 39518907, 2024). "The majority of patients were female (59.1% vs. 66.7% vs. 63.0%, p = 0.796), adenocarcinoma (100% vs. 98.6% vs. 96.3%, p = 0.648), stage IV (100% vs. 95.8% vs. 88.9%, p = 0.236), and EGFR 19DEL mutation (63.6% vs. 52.8% vs. 51.9%, p = 0.642) in the three groups." (PMID 39406371, 2024). "Biologically, these adenocarcinomas differ greatly from adenocarcinomas seen in ever smokers, with differences in the proportion of oncogenic driver mutations such as EGFR, KRAS, and BRAF; these seem to predominate in never smokers, females, and those of east Asian descent." (PMID 39125735, 2024). "Adenocarcinomas harbor mutations of genes of EGFR signaling pathway." (PMID 38953007, 2024). "We also acknowledge that variables such as female sex, Asian ancestry and adenocarcinoma histology, which are associated with EGFR mutation status, may confound our conclusions." (PMID 37020004, 2023). "EGFR gene mutation results in different adenocarcinoma types." (PMID 37340599, 2023). "In fact, we found that patients with adenocarcinoma harboring somatic mutations of EGFR, CTLA4, PDCD1LG2, or ZEB2 that only underwent surgical treatment and developed brain metastases may have the worst prognosis." (PMID 36629526, 2023). "Utilizing the NanoString, Seattle, Washington, United States, nCounter PanCancer Immune Profiling Panel, they discovered that BM from EGFR-mutated adenocarcinoma exhibited increased activation of various immune-related pathways when compared to EGFR-wild-type adenocarcinoma." (PMID 37760494, 2023). "Therefore, the present review aims to describe the multidisciplinary strategies in patients with mNSCLC adenocarcinoma with CNS involvement and EGFR activating mutations or ALK rearrangement." (PMID 36786970, 2023). "In adenocarcinoma patients, 41.6% were positive for EGFR and/or ALK mutations." (PMID 36750899, 2023). "Additionally, approximately one‐third of NSCLC patients, especially those with adenocarcinoma, have been found to harbor epidermal growth factor receptor (EGFR) mutations." (PMID 37425232, 2023). "Therefore, this patient was treated with an EGFR tyrosine kinase inhibitor for EGFR-mutated-stage-IV adenocarcinoma." (PMID 40733862, 2023). "Here, we present a case of EGFR-mutated adenocarcinoma in which a pathological complete response was revealed in histological specimens obtained during conversion surgery following systemic treatment using a third-generation EGFR-TKI." (PMID 39516993, 2023). "Secondly, an absence of pathological confirmation may fail to provide information regarding prognostic factors such as epidermal growth factor receptor (EGFR) mutation in adenocarcinoma, which is also important in guiding adjuvant therapy." (PMID 36890550, 2023). "Consequently, anlotinib emerges as a viable option for patients facing small cell transformation in the context of EGFR-mutated adenocarcinoma." (PMID 38188289, 2023). "The mean age of the total population was 60.1 years old (range 32-77 years), patients (68.89%) were ≤65 years old, 55 patients (61.11%) were male, 75 patients (83.33%) were adenocarcinoma and 40 cases had gene mutation (31 were EGFR+,7 were ALK+, and 2 were ROS1+), 73(81.11%) patients with KPS ≥70." (PMID 37810984, 2023). "EGFR mutation was detected in 216 patients and was significantly more frequent in never smokers, females, lepidic pattern, acinar pattern, and papillary predominant pattern adenocarcinoma." (PMID 35454856, 2022). "In addition to the acquired T790M mutation, the transformation from adenocarcinoma to other components is one of many mechanisms of acquired resistance to an EGFR TKI." (PMID 35543090, 2022).
adenocarcinoma (continued). "The percentage appears to be high in Asia, where non-smoking lung cancer is associated with onset at a young age, advanced stage, adenocarcinoma histology, female gender, and specific EGFR/ ALK/ ROS-1 gene alterations that can be treated with targeted therapeutics." (PMID 36644085, 2022). "Interestingly, the serum carcinoembryonic antigen (CEA) can increase during all adenocarcinomas not only in those EGFR mutated but also in wild type." (PMID 35515138, 2022). "The frequency of EGFR mutation occurrence in adenocarcinomas is 12–48%." (PMID 35740676, 2022). "EGFR mutations were found in 162 tumors; 161 adenocarcinomas, and one pleomorphic carcinoma." (PMID 36115683, 2022). "Histological transformation in EGFR L858R mutated NSCLC (adenocarcinoma)." (PMID 35456982, 2022). "Subsequently, the acquisition of the invasive capabilities may have arisen with the EGFR (Ala289Val) variant, as observed in the adenocarcinoma and adenomatous polyp samples." (PMID 35483879, 2022). "The frequency of pathological invasive factors and EGFR mutation might be related to the malignant behavior of each adenocarcinoma predominance." (PMID 35948946, 2022). "In conclusion, the influence of EGFR-TKIs on the TME in EGFR-mutated adenocarcinoma may play a critical role in the response to immunotherapy." (PMID 35742933, 2022). "This study demonstrated that monitoring EGFR mutation levels or changes in blood could be a meaningful approach to predict clinical response and progression for lung EGFR mutation-positive adenocarcinoma patients treated with TKI therapy." (PMID 35482671, 2022). "Also, the prognostic value of epidermal growth factor receptor (EGFR) mutations in adenocarcinoma was increasingly being understood, which led to further molecular heterogeneity." (PMID 34927371, 2022). "Rare EGFR mutations have been reported to be present at a rate of 12% in adenocarcinoma patients, with G719X having a prevalence of 13.78%, S768I/V having a prevalence of 6.39%, exon 20 insertions having a prevalence of 16.85%, and L861X having a prevalence of 9.88%." (PMID 36613084, 2022). "The authors proposed that a higher percentage of adenocarcinoma in females may be the reason for their predominance in the EGFR mutation rate." (PMID 36341427, 2022). "EGFR is mutated in high frequency in adenocarcinoma and acts in carcinogenesis." (PMID 35565393, 2022). "However, few studies have examined the prognostic factors for RFS by EGFR mutation status in stage IB-IIIA adenocarcinoma patients whose stages are usually indicated for adjuvant therapy." (PMID 36085020, 2022). "If a SCLC diagnosis is confirmed in a never-smoker, the differential diagnosis may include a limited sampling of a combined carcinoma, such as combined SCLC and adenocarcinoma that may harbor EGFR mutations." (PMID 34663914, 2022). "The EGFR incidence of mutation is high in Asian: up to 50% adenocarcinomas bearing EGFR mutations." (PMID 35978836, 2022). "This could explain why there was better TTF duration in adenocarcinoma patients with EGFR mutation in our study." (PMID 34841687, 2022). "Among those screened 44 patients (20%) had adenocarcinoma harboring EGFR mutations." (PMID 35847912, 2022).
adenocarcinoma (continued). "The sequencing of 3243 patient-derived human adenocarcinoma tumor tissues revealed the following mutations along with their incidence: EGFR (55.9%), KRAS (11.7%), NRAS (0.7%), PIK3CA (2.9%), HER2 (2.1%), BRAF (1.6%); fusions of ALK (2.8%), ROS1 (0.6%), RET (0.6%), and amplifications in MET (1.3%)." (PMID 35008313, 2021). "Additionally, previous studies have shown that GGO nodular lung adenocarcinoma had a higher frequency (up to 63%) of EGFR mutations than other types of adenocarcinoma." (PMID 34109114, 2021). "Consequently, our study reviewed data for 827 patients with adenocarcinoma to assess the association between CT and clinical characteristics and EGFR and ALK mutations." (PMID 33707479, 2021). "One possible explanation for the higher rate of EGFR mutation could be differences in histological subgroups proportions, as the study demonstrated up to 78% of adenocarcinoma subgroup in comparison with our cohort that reported 65%." (PMID 33956842, 2021). "Information on EGFR mutation status was available in 33 patients with adenocarcinoma." (PMID 34181677, 2021). "We propose that EGFR mutation occurred in the development of adenocarcinoma." (PMID 33442956, 2021). "The lobulation is associated with more EGFR mutation in adenocarcinoma than the wild-type EGFR." (PMID 34439100, 2021). "Adenocarcinoma was diagnosed in 13 patients, and three of them harboring EGFR mutations." (PMID 33931705, 2021). "Gene mutations could be safely demonstrated from the effusion cfDNA fraction obtained from adenocarcinoma patients, 3/36 EGFR, 9/36 KRAS and 1/36 BRAF gene variants were detected." (PMID 34257581, 2021). "EGFR mutations were more common in lepidic predominant adenocarcinoma." (PMID 34026636, 2021). "Based on clinical trials showing improvement of progression‐free survival (PFS) following treatment with first‐ and second‐generation EGFR tyrosine kinase inhibitors (TKIs), EGFR TKIs have become the first‐line treatment for EGFR mutation‐positive adenocarcinomas." (PMID 33586356, 2021). "Previous studies have found that concomitant KRAS and EGFR mutations may increase the cell death rate of adenocarcinoma cells through hyperactivation of ERK signaling." (PMID 34921211, 2021). "Although immunotherapy, such as immune checkpoint inhibitors (ICIs), has recently been highlighted, epidermal growth factor receptor (EGFR) tyrosine kinase inhibitors (TKIs) are recommended as a first‐line therapy for patients with advanced adenocarcinoma with EGFR mutation." (PMID 33529490, 2021). "P01, P03, P06 and P07 were adenocarcinomas, and EGFR 19del or EGFR L858R mutation was detected." (PMID 34336662, 2021). "In the case of adenocarcinoma, in particular, driver mutations and the corresponding drugs already exists and thus, it reacts well to targeted therapy, which includes, but is not limited to EGFR, ALK, and ROS1, resulting in good outcomes." (PMID 33422052, 2021). "Eighty-seven patients were with EGFR mutations, and 104 adenocarcinomas were EGFR-wildtype or unknown." (PMID 34286335, 2021). "Likewise, a study involving 111 patients with adenocarcinoma with EGFR mutation found that exon 19 deletion was independently associated with acquired T790M mutation (p = 0.003) in a multivariable analysis." (PMID 33529490, 2021). "The incidence of pleural invasion and EGFR mutation was higher in STAS+ adenocarcinoma." (PMID 34249691, 2021). "In conclusion, rebiopsy might influence the clinical course in adenocarcinoma patients with EGFR mutation who received EGFR‐TKI." (PMID 33529490, 2021). "A total of 352 patients with adenocarcinoma and EGFR mutations were included in this study." (PMID 33529490, 2021). "Twenty‐one patients had adenocarcinoma, of which four patients harbored EGFR mutations." (PMID 33934572, 2021).
adenocarcinoma (continued). "Concordant with previous molecular studies, major driver events in adenocarcinoma, namely EGFR activating mutations, ALK gene rearrangement and ROS1 gene rearrangement, were rarely present in pulmonary LELC, indicating that they were less important events in the pathogenesis of pulmonary LELC." (PMID 32726920, 2020). "EGFR mutations or deletions are one of the most common driver mutations found in NSCLC adenocarcinoma and reliable identification of alterations in EGFR in NSCLC patients is critical to correctly identify patients that will benefit from treatment with tyrosine kinase inhibitors." (PMID 33260345, 2020). "Interestingly, the cohort of Vietnamese patients with advanced adenocarcinoma had higher prevalence of EGFR mutations than the Caucasian MSK-IMPACT cohort." (PMID 32066856, 2020). "We observed an EGFR mutation frequency of 24.0% among the adenocarcinoma stage IV patients, in line with previous Brazilian estimates, which was higher than that in North America and Europe (for which EGFRm frequencies usually range from 10-20%) and lower than that in Asia (as high as 50%)." (PMID 33084767, 2020). "EGFR mutations are more likely found in c-SCLC with adenocarcinoma component." (PMID 32494919, 2020). "However, almost every transformed SCLC retained the original EGFR activating mutation of the parent adenocarcinoma and, correspondingly, strong and durable response to EGFR TKIs were found initially." (PMID 35582610, 2020). "Therefore, NSCLC patients, especially adenocarcinoma patients, are recommended to undergo EGFR mutation testing." (PMID 32103127, 2020). "Notably, 46 patients (43%) had adenocarcinoma, including two patients with epidermal growth factor receptor (EGFR) mutations, four patients with anaplastic lymphoma kinase (ALK) rearrangements, and one patient with ROS1 mutation." (PMID 32057187, 2020). "To further understand the role of CEA heterogeneity in lung tumors, we divided adenocarcinomas with EGFR mutations into four groups based on CEAIn and CEAPd levels and discovered that patients displaying high CEAIn but low CEAPd levels tended to develop new metastasis." (PMID 32034239, 2020). "On histopathological examination and immunohistochemistry analysis, forceps biopsy only yielded fragmented bronchial epithelium with rare atypical cells while cryobiopsy yielded adenocarcinoma lung with sensitizing epidermal growth factor receptor (EGFR) mutation." (PMID 32493437, 2020). "Our analysis of the TCGA cohort showed that a subset of pro-tumorigenic integrins, including α1β1, α2β1, α3β1, α5β1, and α6β4, were frequently amplified or upregulated at the genomic or mRNA level in KRAS or EGFR mutation/overexpression-enriched adenocarcinomas." (PMID 32793596, 2020). "However, targetable mutations in PSC are less frequent than in NSCLC with adenocarcinoma histology, with EGFR mutations reported in 8-22% cases in various studies." (PMID 32149365, 2020). "The median age was 55 years (range, 23–80 years), prevalent histology was adenocarcinoma (87.5%), and epidermal growth factor receptor (EGFR) mutation status was detected in 109 patients (18.6%), including 57 patients of wild-type and 52 patients of mutant type." (PMID 33194635, 2020). "Univariate analysis revealed that female, KPS ≥90, BMI ≥24.0, adenocarcinoma, EGFR or ALK positive, significantly decreased the death risk of patients, but ECM (especially organ numbers ≥3), BM numbers ≥4, N2~N3, and smoking (especially current smoking) increased it." (PMID 33027555, 2020). "This study specifically included a lower percentage of adenocarcinoma, which may have contributed to lower incidence of EGFR mutations." (PMID 30760227, 2019). "They further identified several factors, including female gender, adenocarcinoma, distant metastasis, and the chemotherapy, that may increase the probability of EGFR gene mutations." (PMID 31144459, 2019).
adenocarcinoma (continued). "The overall frequency of the EGFR mutation was found in 28% (14 of 50) of the adenocarcinomas." (PMID 31531095, 2019). "Among the 309 patients, a total of 163 (52.8%) adenocarcinomas showed EGFR mutation." (PMID 30956990, 2019). "The stage IIIA adenocarcinoma case was found to carry an additional EGFR exon 19 deletion mutation." (PMID 31369639, 2019). "All patients had adenocarcinoma with confirmed sensitizing EGFR mutations." (PMID 31602787, 2019). "Molecular testing was predominantly undertaken in patients with adenocarcinoma for epidermal growth factor receptor (EGFR) mutation, although in the initial stages of this study such testing was undertaken after discussion at the MDM since the test did not have Government remuneration." (PMID 31429741, 2019). "Although targeted therapy against adenocarcinoma with epidermal growth factor receptor (EGFR) gene mutation or anaplastic lymphoma kinase (ALK) and ROS1 proto-oncogene receptor tyrosine kinase (ROS1) rearrangements have shown dramatic effects, few targeted therapies against SCC have been identified." (PMID 31481045, 2019). "Patients with EGFR gene mutations common in adenocarcinoma have a low benefit from the ICIs therapy, what may confirm the differences between SCC and AD." (PMID 31010080, 2019). "Therefore, a nomogram that can predict survival probability by incorporating epidermal growth factor receptor mutation status and treatments for patients with advanced adenocarcinoma would be highly valuable." (PMID 31419239, 2019). "In addition, DMPs significantly associated with NSCLC in current smokers, the EGFR mutation status in patients with adenocarcinoma, and the survival rate in patients with advanced-stage NSCLC were identified." (PMID 31450665, 2019). "The most prevalent history of disease included the incidence of adenocarcinoma (96.3%), 10 patients (37.0%) had relapse after surgery, and all the patients had exon 19 deletion or an L858R deletion in exon 21; these were the most common mutation types in EGFR." (PMID 30875919, 2019). "The intratumoral heterogeneity of the EGFR L858R mutation might be associated with the gefitinib response in patients with adenocarcinoma NSCLC harboring the mutation." (PMID 31014278, 2019). "One of the most important mutations, especially in adenocarcinoma, is EGFR mutations." (PMID 31870098, 2019). "This phenomenon may be because EGFR mutations appear more frequently in lepidic predominant adenocarcinomas, which are associated with better outcomes." (PMID 31783917, 2019). "Thus, this study aimed to develop and validate a set of prognostic models incorporating demographic, clinical, and treatment-related characteristics according to the EGFR mutation status of Asian patients with advanced stage adenocarcinoma." (PMID 31419239, 2019). "EGFR-mutated adenocarcinoma frequently develops via the multistep progression." (PMID 29690599, 2018). "In certain regions testing at initial diagnosis for EGFR mutation remains quite low and may occur at a rate of 22.6% for stage IV adenocarcinoma patients." (PMID 29755953, 2018). "The postoperative prognosis of Mt patients might differ according to the major EGFR mutation among resectable advanced and recurrent adenocarcinomas of the lung." (PMID 30290774, 2018). "EGFR mutations were predominantly found in adenocarcinoma (270 patients, 96.4%)." (PMID 29447182, 2018). "However, according to a recent systematic review and global map of EGFR mutation incidence in NSCLC, the frequency of EGFR mutations among adenocarcinoma patients in the Asia-Pacific area ranges from 20% to 76%, and the mean frequency is 57% in Taiwan." (PMID 29447182, 2018). "However, the patient had a good treatment response and prolonged PFS, and the original activating EGFR mutations of adenocarcinoma persisted in the re-biopsy SCLC specimens." (PMID 29455650, 2018).